ENSG00000227863 (novel transcript)
Synonyms: PRALR; LOC105375387
Gene: Long non-coding RNA gene on chromosome 7 (89,354,192 to 89,496,918, forward strand). Ensembl gene ENSG00000227863.
Diseases named in the same sentence as ENSG00000227863 in open-access papers:
ENSG00000227863 is named in the same sentence as 2 diseases in open-access papers, as found by Europe PMC text mining. Sharing a sentence is not in itself a finding about the gene and the disease.
ENSG00000227863 shares sentences with these, for which no sentence is quoted: breast carcinoma (1 paper); prostate carcinoma (1).